ULBP2 (UL16 binding protein 2)
Diseases named in the same sentence as ULBP2 in open-access papers (continued):
Sharing a sentence is not in itself a finding about the gene and the disease.
COVID-19 (5 papers, 2021 to 2025). A disease caused by infection with severe acute respiratory syndrome coronavirus 2. "For example, severe COVID-19 patients had higher levels of the soluble form of ULBP2, a ligand for the NKG2D receptor on NK cells that mediates mediating cytotoxicity, which inhibits NK-cells as a mechanism to evade immunosurveillance by NK cells." (PMID 35177642, 2022). "Soluble forms of other NKG2D-related ligands, ULBP2 and ULBP3, were also found to be significantly increased among COVID-19 patients suffering from severe infection, and their levels correlated with decreased expression of NKG2D." (PMID 41153412, 2025). "These analyses revealed that SARS-CoV-2 infection was associated with significant increases in levels of mRNA for the NKG2D ligands, ULBP2 and ULBP3 in COVID-19 patients with severe disease." (PMID 38410511, 2024). "ULBP2, SYT2, VMAC, and FOXJ1 followed the same pattern of expression in COPD compared to COVID-19, however, to a much lower level." (PMID 33679887, 2021).
hepatocellular carcinoma (5 papers, 2017 to 2025). A malignant tumor that arises from hepatocytes. "IL-32α is involved in the progression of hepatocellular carcinoma, but the overexpression of IL-32α enhances natural killer cell-mediated killing by upregulating the expression of Fas and UL16 binding protein 2 (ULBP2) in human chronic myelogenous leukemia cells, exerting an anti-cancer effect." (PMID 38584169, 2024). "Cisplatin can suppress the androgen receptor (AR) expression by increasing miR-34a-5p to suppress AR expression, and the inhibited AR may function through upregulation of ULBP2 protein, thereby enhancing NK cell function and preventing hepatocellular carcinoma progression." (PMID 36313765, 2022).
colorectal cancer (4 papers, 2014 to 2025). A primary or metastatic malignant neoplasm that affects the colon or rectum. "In HCT116 colorectal carcinoma cell lines, the knockdown resulted in a significant increase of ULBP2 of more than 30%; similarly, we observed an increase of about 15% for ULBP2 in 293T upon IMP3 loss this cell line." (PMID 26982091, 2016). "UL16 binding protein 2 (ULBP2), an MHC class I-related molecule, is minimally expressed in normal tissues but is highly upregulated in tumor tissues, including pancreatic and colorectal cancers." (PMID 40775202, 2025).
endometriosis (4 papers, 2015 to 2025). The growth of functional endometrial tissue in anatomic sites outside the uterine body. "A prospective study showed that ULBP2 expression in the peritoneal fluid of women with endometriosis was significantly high and was related to disease severity." (PMID 34266418, 2021). "For this reason, we assayed peritoneal fluid NKG2DLs (MICA, MICB and ULBP-2) obtained from patients with histologically proven endometriosis and endometriosis-free women." (PMID 25775242, 2015). "Statistical analyses for peritoneal NKG2D ligands (MICA, MICB and ULBP-2) ratio levels in women with endometriosis and controls." (PMID 25775242, 2015). "Clinical, surgical and biological correlations with peritoneal fluid MICA, MICB and ULBP-2 levels in women with endometriosis are expressed in S3 Table." (PMID 25775242, 2015). "When samples with undetectable peritoneal fluid levels of MICA, MICB and ULBP-2 were excluded, MICA ratio levels were significantly higher in endometriosis patients than in controls (median, 1.1 pg/mg; range, 0.1–143.5 versus median, 0.6 pg/mg; range, 0.1–3.5; p=0.003)." (PMID 25775242, 2015).
glioblastoma (4 papers, 2019 to 2024). The most malignant astrocytic tumor (WHO grade IV). "As expected, all the tested glioblastoma cell lines expressed high levels of NKG2DLs, particularly ULBP2." (PMID 31288857, 2019). "ADAM10 and ADAM17 are expressed at high levels on the surface of glioblastoma-initiating cells thus contributing to an immunosuppressive phenotype through the ULBP2 cleavage." (PMID 31736972, 2019). "Specific inhibition of these enzymes preserved cell surface ULBP2 leading to increased glioblastoma cell recognition and killing by NK cells." (PMID 31736972, 2019). "As expected, all the tested glioblastoma cell lines expressed high levels of NKG2DL, particularly ULBP2/5/6." (PMID 39877353, 2024). "Three representative glioblastoma cell lines (U251, U87, A172) were selected for assessing cell surface expression of NKG2DL (MICA/B, ULBP1, ULBP2/5/6, ULBP3, and ULBP4) by flow cytometry." (PMID 39877353, 2024). "Cell surface expression of the main ligands for the NKG2D receptor (MICA, MICB, ULBP1, ULBP2, and ULBP3) on the glioblastoma cell lines, U-251MG, T98G, and U-87MG, was assessed by flow cytometry." (PMID 31288857, 2019). "Next, the co-expression of the glioblastoma stem cell marker NESTIN and NKG2DLs (MICA, MICB, ULBP1, ULBP2, ULBP3) in these suspended cell spheres was assessed by flow cytometry." (PMID 31288857, 2019).
HCMV infection (4 papers, 2014 to 2018). "The NKG2DL MICB and ULBP2 are strongly upregulated during HCMV infection, but fail to reach the cell surface as they are retained in the ER by the NK evasion function gpUL16." (PMID 28186488, 2017). "HCMV infection strongly induces transcription of MICB, ULBP1, and ULBP2 mRNA but prevents their surface expression by intracellular sequestration with HCMV UL16." (PMID 24906157, 2014). "At no stage during the replication cycle did HCMV infection induce an up regulation MICA, MICB, or ULBP2 expression at the cell surface." (PMID 24787765, 2014).
malignant glioma (4 papers, 2014 to 2023). A grade III or grade IV glioma arising from the central nervous system. "Secondly, transforming growth factor-β (TGF-β), a tumor cytokine, has been reported to selectively suppress the transcription and protein expression of MICA, ULBP2 and ULBP4 on malignant glioma cells." (PMID 28159927, 2017). "Additionally, transforming growth factor-beta (TGF-beta) selectively downregulates the expression of MICA, ULBP2, and ULBP4, but not MICB, ULBP1, or ULBP3, in malignant glioma cells." (PMID 24885711, 2014).
myeloma (4 papers, 2016 to 2022). "A number of other studies have demonstrated the expression of MICA and/or ULBP2 in senescent cells derived from different cell types, namely human activated stellate cells, replicative senescent human umbilical vein endothelial cells and chemotherapy-induced senescent multiple myeloma cells." (PMID 26878797, 2016). "We analyzed the morphology of the patient primary myeloma cells for expression levels of MHC I, MICA, MICB, ULBP1, ULBP2/5/6, HLA-E, CD38 (n = 12), CD112, CD155, ICAM-1 and PD-L1 (n =5) using flow cytometry." (PMID 35413499, 2022). "In other study, valproic acid (VPA) induced the upregulation of MICA/B and ULBP2 in MM cell lines and patients’ myeloma cells, and, consequently, degranulation and cytotoxic activity of NK cells were enhanced in presence of VPA-pretreated myeloma cells." (PMID 33802806, 2021).
osteosarcoma (4 papers, 2012 to 2021). A usually aggressive malignant bone-forming mesenchymal neoplasm, predominantly affecting adolescents and young adults. "Osteosarcoma expresses the intriguing hit UL16 binding protein 2 (ULBP2), which is a ligand for the NK cell activation marker NKGD2." (PMID 23251904, 2012). "Interestingly, some NKG2D ligands (MICA, MICB, ULBP-2 and ULBP-3) are secreted from NSCLC, osteosarcomas and gastric cancer cells and may be shed by MMP-mediated cleavage." (PMID 34638439, 2021).
B-cell chronic lymphocytic leukemia (3 papers, 2016 to 2024). "More recently, a trifunctional NKCE targeted NKG2D/ULBP2–aCD19–aCD33 was reported to combat chronic lymphocytic leukaemia." (PMID 39472273, 2024). "The prognostic value of ULBP2 was also reported in B-cell chronic lymphocytic leukemia (CLL), and the expression in 98 patients with CLL and 48 healthy participants as the control group was analyzed by means of ELISA." (PMID 33909599, 2021). "A mono-targeting triple body ULBP2-aCD19-aCD19 and a dual-targeting triple body ULBP2-aCD19-aCD33 were constructed to recruit NK cells to kill CD19- or CD33-positive chronic lymphocytic leukemia cells." (PMID 28036020, 2016).
medulloblastoma (3 papers, 2013 to 2023). A malignant, invasive embryonal neoplasm arising from the cerebellum. "Major histocompatibility complex class I-related chain A (MICA), CD1d and UL16 binding protein 2 (ULBP-2) are cell surface ligands of medulloblastoma, that bind NK cell activating receptor NKG2D." (PMID 36792722, 2023). "MICA/ULBP-2 positive cells and intensity of cytoplasmic staining by immunohistochemistry on medulloblastoma tumors." (PMID 23626949, 2013).
AIDS (2 papers, 2011 to 2021). A syndrome resulting from the acquired deficiency of cellular immunity caused by the human immunodeficiency virus (HIV). "Similarly, in individuals with acquired immune deficiency syndrome (AIDS), HIV-1 decreases the cell surface expression of MICA, ULBP1 and ULBP2 in infected cells through Nef protein, which decreases the susceptibility of the virus to NK cell-mediated lysis." (PMID 34400893, 2021).
chronic pancreatitis (2 papers, 2014 to 2018). A chronic inflammatory process causing damage and fibrosis of the pancreatic parenchyma. "In addition, the detection in serum of MIC-1 in combination with UL16 binding protein 2 (ULBP2) was found to improve the accuracy of differentiation between patients with PC and patients with chronic pancreatitis or healthy individuals." (PMID 29662668, 2018).
colon adenocarcinoma (2 papers, 2022 to 2023). "A report showed that RAET1L together with ULBP1, ULBP2, ULBP3 had the high diagnostic values in colon adenocarcinoma (COAD)." (PMID 36294477, 2022).
HIV-1 infection (2 papers, 2011 to 2018). The type species of lentivirus and the etiologic agent of acquired immunodeficiency syndrome (AIDS). "It would seem likely that NK cells would be skewed toward killing infected cells since HIV-1 infection leads to increased expression of ICAMs on the infected cell surface, induces expression of ULBP-1 and ULBP-2, and down modulates HLA-A and HLA-B." (PMID 21994772, 2011).
leukemia (2 papers, 2017 to 2022). A malignant (clonal) hematologic disorder, involving hematopoietic stem cells and characterized by the presence of primitive or atypical myeloid or lymphoid cells in the bone marrow and the blood. "All experiments were performed to investigate specifically the efficacy of the employed ULBP2-aCD19-aCD33 against only CD19/CD33-expressing leukemia cells, which are mainly found in resistant antigen loss variants especially described as mixed lineage leukemia (MLL)." (PMID 28943878, 2017). "Similar to our cytotoxic assays with the (ULBP2-aCD19-aCD33) TBs in response to leukemia cell lines and primary AML blasts, designed NKG2D-stimulating TBs that contained targeting against CD19 antigens (ULBP2-aCD19-aCD19) only displayed strong affinity to CD19 surface molecules on CLL cells." (PMID 28943878, 2017). "In our experiments, we could confirm the effectiveness of the (ULBP2-aCD19-aCD33) TBs in the crosslink with activated NK cells showing increased specific killing against a leukemia cell line (BV-173) and primary AML samples from three different patients compared to single use of NK cells only." (PMID 28943878, 2017).
lung adenocarcinoma (2 papers, 2019 to 2021). A carcinoma that arises from the lung and is characterized by the presence of malignant glandular epithelial cells. "Our results showed that ULBP1 and ULBP2/5/6 are predominantly expressed in lung squamous cell carcinoma, while ULBP4 is expressed in lung adenocarcinoma." (PMID 31827723, 2019). "Interestingly, ULBP1 or ULBP2/5/6 tend to be overexpressed in lung squamous cell carcinoma, while ULBP4 is largely overexpressed in lung adenocarcinoma." (PMID 31827723, 2019).
non-small cell lung carcinoma (2 papers, 2021 to 2024). A group of at least three distinct histological types of lung cancer, including non-small cell squamous cell carcinoma, adenocarcinoma, and large cell carcinoma.
anaplastic cancer (1 paper, 2024). "Studies on RAETL1 in thyroid cells demonstrated that anaplastic cancer cell lines are sensitive to NK cell-mediated lysis via ULBP2/5/6 and chemoattractant CXCR3-positive NK cells, suggesting that patients with ATC may benefit from NK cell-based immunotherapy." (PMID 38610938, 2024).
astrocytoma (1 paper, 2011). "Constitutive levels of NKG2D ligands are low in most cells, thus, to examine the effect of U21 upon the surface expression of the NK ligands, we generated U373 astrocytoma cell lines individually stably expressing ULBP1, ULBP2, ULBP3, MICA, or MICB, using retrovirus-mediated gene transfer." (PMID 22102813, 2011).
breast tumor (1 paper, 2012). "Most of the NKG2D ligands examined in this study were frequently expressed among the breast tumor cohort: MIC-AB in 50% of the cases; ULBP-1 in 90%; ULBP-2 in 99%; ULBP-3 in 100%; ULBP-4 in 26%; and ULBP-5 in 90%." (PMID 22257486, 2012). "We have shown in this study, for the first time, that breast tumors may express all of the known NKG2D ligands and that expression of MIC-AB and ULBP-2 results in a favorable outcome concerning RFP." (PMID 22257486, 2012).
capillary hemangioma (1 paper, 2024). A common hemangioma characterized by the presence of capillary-sized vascular channels without prominent epithelioid endothelial cells. "This has been attributed to the unexpected binding to vascular endothelial growth factor receptor 2, frizzled class receptor 5, and UL16 binding protein 2 that may correlate with the side effects of capillary hemangiomas observed in clinical studies with camrelizumab." (PMID 38176728, 2024).
head and neck squamous cell carcinoma (1 paper, 2012). A squamous cell carcinoma that arises from any of the following anatomic sites: lip and oral cavity, nasal cavity, paranasal sinuses, pharynx, larynx, and salivary glands. "For example, proteasome inhibition specifically upregulated ULBP2 in Jurkat cells, but ULBP1 in head and neck squamous cell carcinoma (HNSCC) cells." (PMID 23056001, 2012).
laryngeal carcinoma (1 paper, 2023). Carcinoma that arises from the laryngeal epithelium. "In HNSCC, including tonsil and laryngeal cancers, ULBP2 had the highest expression level, ULBP1 had the highest, lowest, and ULBP3 was in between." (PMID 37565867, 2023). "In laryngeal cancer, the expression levels of ULBP1/3 correlated with poor prognosis (P < .05), whereas ULBP2 expression was not significantly correlated with prognosis (P = .269)." (PMID 37565867, 2023).
liver cancer (1 paper, 2023). An epithelial or non-epithelial malignant neoplasm that arises from the liver. "A mechanistic study involving reprogrammed CSCs from liver cancer revealed that CD44 mRNA functions as a competing endogenous RNA (ceRNA) that specifically binds microRNA (miR)-34a, thereby preventing the activating NKG2DL, UL16 binding protein 2 (ULBP2), from degradation." (PMID 38164743, 2023).
lymph node metastasis (1 paper, 2016). "A significant difference was observed in the serum ULBP2 levels with regard to the CA199 levels (p=0.013),lymph node metastasis (p=0.009) and overall survival(p=0.045)." (PMID 27602753, 2016). "Moreover, a significant difference was noted in the serum ULBP2 level with regard to the CA199 levels and lymph node metastasis." (PMID 27602753, 2016).
malignant brain tumors (1 paper, 2013). "Major histocompatibility complex class I-related chain A (MICA) and UL16 binding protein 2 (ULBP-2) are tumor cell surface ligands that bind NK cell activating receptor NKG2D, and are prevalent in malignant brain tumors." (PMID 23626949, 2013).
prostate tumor (1 paper, 2014). "Variable NKG2D-ligand expression was observed in different PC lines, but all prostate tumor cells examined were positive for ULBP-2 and MICA/B ligands." (PMID 25268476, 2014).
reovirus infection (1 paper, 2023). "To uncover the mechanism by which reovirus infection leads to the reduced expression of MICA, MICB, ULBP2, and ULBP3 in infected cells, we first evaluated their shedding from the cell surface." (PMID 37753084, 2023). "Downregulation of the surface expression of MICA, ULBP2, and ULBP3 was observed in both MNT-1 and U87-MG cells following reovirus infection." (PMID 37753084, 2023). "Thus, we further tested whether the intracellular protein levels of MICA, MICB, ULBP2, and ULBP3 were altered upon reovirus infection." (PMID 37753084, 2023).
sarcoma (1 paper, 2020). A usually aggressive malignant neoplasm of the soft tissue or bone. "We observed that the high expression of DNAM-1 ligand CD155 as well as the high expression of NKG2D ligands ULBP1, ULBP2, and ULBP3 are negatively associated with survival in sarcoma patients." (PMID 32082316, 2020).
squamous cell carcinoma (1 paper, 2019). A carcinoma arising from squamous epithelial cells. "Either ULBP1 or ULBP2/5/6 overexpression was associated with squamous-cell carcinoma histology, whereas ULBP4 overexpression was associated with younger age and adenocarcinoma histology." (PMID 31827723, 2019). "Interestingly, either ULBP1 or ULBP2/5/6 overexpression was correlated with a squamous cell carcinoma histology, while ULBP4 overexpression was correlated with younger age and adenocarcinoma histology." (PMID 31827723, 2019). "Our data suggested that an antibody type drug targeting ULBP1 or ULBP2/5/6 might be appropriate for the treatment of squamous cell carcinoma whereas one targeting ULBP4 might be useful for treating adenocarcinoma, as more than a half of studied tumors expressed each of these molecules, respectively." (PMID 31827723, 2019).
tonsil cancer (1 paper, 2023). A primary or metastatic malignant neoplasm that affects the tonsil. "In patients with tonsil cancer, those with a high expression level of ULBP2/3 had a worse prognosis, whereas the opposite was true for those with a low expression level, possibly because of the expression of more soluble ligands." (PMID 37565867, 2023).
viral infection (1 paper, 2025). "Based on these findings, we consider that measuring serum sULBP2 levels could serve as an indirect indicator of ULBP2 expression on cell surfaces, potentially aiding in the assessment of the impact of viral infection on NK cells." (PMID 40421029, 2025). "UL-16 binding protein 2 (ULBP2), a ligand for the activating receptor NKG2D on NK cells, is induced on the surfaces of host cells during viral infection, leading to NK cell activation." (PMID 40421029, 2025). "Because sULBP2 is considered a potential surrogate maker of cell surface ULBP2 that stimulates NK cells through NKG2D, NK cells may be strongly stimulated during viral infection." (PMID 40421029, 2025).
vitiligo (1 paper, 2012). Generalized well circumscribed patches of leukoderma that are generally distributed over symmetric body locations and is due to autoimmune destruction of melanocytes. "One of the well-known ligands in the ULBP family—ULBP2, has been up-regulated in vitiligo skin in our microarray analysis as well (around 1.5 folds increase in vitiligo skin), although the data did not meet our strict cut-off criteria (at 2 fold)." (PMID 23251420, 2012).
ZIKV infection (1 paper, 2019). "We found that Vδ2 T-cells express high level of NKG2D and, on the other hand, ZIKV infection induced an up-regulation of MICA/B and ULBP2 on target cells, making them more susceptible to NKG2D-mediated lysis." (PMID 31547470, 2019). "Moreover, ZIKV infection was able to increase the expression on A549 cells of NKG2D ligands (NKG2DLs), namely MICA, MICB, and ULBP2, at both the mRNA and protein levels, suggesting the possible involvement of these molecules in the recognition by NKG2D-expressing Vδ2 T-cells." (PMID 31547470, 2019).